TMEM119 (transmembrane protein 119)
Diseases named in the same sentence as TMEM119 in open-access papers (continued):
Sharing a sentence is not in itself a finding about the gene and the disease.
glioblastoma (4 papers, 2021 to 2024). The most malignant astrocytic tumor (WHO grade IV). "Collectively, these data suggest P2RY12 and TMEM119 are robust discriminators of microglia and TAMs in human tissue, both in epilepsy tissue and in the context of glioblastoma." (PMID 34286275, 2021). "In this study, we demonstrate the translatability of microglial-specific genes P2RY12 and TMEM119 in robustly discriminating microglia and TAMs in fluorescently stained human glioblastoma tissue." (PMID 34286275, 2021). "From our staining, we determined P2RY12 and TMEM119 were the best markers for the delineation of microglia and TAMs and subsequently used these to define populations across epilepsy, meningioma, low-grade, and glioblastoma tumor tissue." (PMID 34286275, 2021). "P2RY12 and TMEM119 successfully discriminated microglia from TAMs in glioblastoma." (PMID 34286275, 2021). "Patients in the microglia-high cohort based on P2RY12 immunoreactivity had significantly longer survival times in glioblastoma, and although a similar trend was observed with TMEM119 microglial density, this was not statistically significant." (PMID 34286275, 2021). "Tissue sections from resected low-grade, meningioma, and glioblastoma (grade IV) tumors and epilepsy tissues were immunofluorescently triple-labeled for Iba1 (pan-myeloid marker), CD14 or CD163 (preferential TAM markers), and either P2RY12 or TMEM119 (microglial-specific markers)." (PMID 34286275, 2021).
Brain Tumor (3 papers, 2021 to 2025). "The previous study also showed that many TMEM119+ microglia cells were recruited and surrounded the brain tumors in a murine astrocytoma model." (PMID 39781357, 2025).
COVID-19 (3 papers, 2023 to 2025). A disease caused by infection with severe acute respiratory syndrome coronavirus 2. "Postmortem human COVID-19 brains contained TMEM119+ microglia co-expressing viral antigens, ACE2, and NLRP3, while infection of K18-hACE2 mice induced NLRP3 upregulation in brain tissue." (PMID 41305454, 2025). "Compared to healthy controls, individuals with post-COVID-19 revealed a high percentage of TMEM119+P2RY12+CD68+Iba1+HLA-DR+CD11c+SCAMP2+ microglia assembled in prototypical cellular nodules." (PMID 39060438, 2024). "Considering the relatively short hospitalization time prior to death of our COVID-19 cohort (14.5 days), and the similar immunoreactivity pattern compared to other available studies, it could be inferred that TMEM119 downregulation does not occur early in COVID-19." (PMID 36781876, 2023).
diabetes (3 papers, 2021 to 2023). "However, the lower expression of TMEM119 in diabetes compared with healthy pancreatic islets points to further potential mechanisms of effect in the comorbidity." (PMID 37433298, 2023).
hepatocellular carcinoma (3 papers, 2021 to 2025). A malignant tumor that arises from hepatocytes. "Using the TIMER database, TMEM119 was found to be upregulated in STAD, as well as in other cancers, such as hepatocellular carcinoma, head and neck squamous cell carcinoma, and cholangiocarcinoma (P < 0.05)." (PMID 40219804, 2025).
prion disease (3 papers, 2019 to 2026). A transmissible disease that is caused by a protein that is able to induce abnormal folding of normal cellular proteins, leading to characteristic spongiform brain changes, which are associated with neuronal loss without an inflammatory response. "Although Tmem119 is considered a marker of homeostatic microglia, its per-cell expression remains relatively stable during prion disease progression." (PMID 41504596, 2026). "The loss of homeostatic microglial proteins is visible in immunofluorescence double-staining of IBA1 and TMEM119 in terminally sick mice and mock-infected healthy control brains, and shows the reciprocal regulation of both proteins in prion disease." (PMID 36230910, 2022). "In contrast, the microglia homeostasis marker TMEM119 was downregulated upon prion disease in both cohorts." (PMID 31118110, 2019). "As previously shown, TMEM119-positive processes are highly reduced at the terminal stage of prion disease in the hippocampus, and almost completely lost in the thalamus during terminal prion disease." (PMID 36230910, 2022). "Although P2Y12 expression in individual microglia is known to be markedly downregulated as prion disease progresses, IBA1+ cells exhibiting neuronal envelopment were found to be positive for both TMEM119 and P2Y12." (PMID 41504596, 2026). "We recently showed that the abundance of homeostatic microglia proteins such as TMEM119 and P2RY12 is significantly reduced in terminal prion disease." (PMID 36230910, 2022).
dementia (2 papers, 2022 to 2026). Loss of intellectual abilities interfering with an individual's social and occupational functions. "We primarily used CD68 as a marker of phagocytic microglia, as well as other markers of microglia including Iba‐1 and TMEM119, and the myeloid cell marker TREM2 to assess dementia‐specific changes." (PMID 35748290, 2022).
hematoma (2 papers, 2022). A hematoma is a collection of blood from a vascular structure into an extravascular space. "The number of TMEM119-positive cells was markedly increased in the peri-hematoma tissue at 24 h after ICH, while treatment with Didymin diminished the number of TMEM119-positive cells." (PMID 35154128, 2022). "Simultaneously, there was a marked stromal accumulation of F4/80-positive and TMEM119-negative leukocytes, presumably reflecting the peripheral blood recruitment of monocyte-derived macrophages, which play a key role in early hematoma resolution and detoxification of its degradation products." (PMID 36482445, 2022).
melanoma (2 papers, 2022 to 2024). A malignant, usually aggressive tumor composed of atypical, neoplastic melanocytes. "For LDB2 and TMEM119 the highest mutation rate was in TCGA-SKCM, a melanoma study and was followed immediately by TCGA-UCEC." (PMID 34791179, 2022).
tauopathy (2 papers, 2018 to 2025). Neurodegenerative disorders involving deposition of abnormal tau protein isoforms (tau proteins) in neurons and glial cells in the brain. "Furthermore, within the tauopathy mouse model, we found a strong association between CXCR4 and TMEM119 and AIF1 within the hippocampus." (PMID 29636460, 2018). "The alterations of CX3CL1, TMEM119, and CD4 in subjects with tauopathy also displayed a similar pattern of inflammatory changes." (PMID 40842561, 2025).
viral infection (2 papers, 2018 to 2021). "In regions with more prolonged viral infection (i.e., the rostral region of the brain), infiltrating Ly6Chi macrophages had lower Ly6C expression and higher expression of CX3CR1, TMEM119, P2RY12, CD64, CD68 and MHC-II, compared to those in the caudal regions." (PMID 34311763, 2021). "Leukocytes identified by CD45-immunohistochemistry and Giemsa staining, whilst being P2Y12- and Tmem119-negative have been found at sites of virus infection in close vicinity of HSV-1-positive cells and microglia." (PMID 30027450, 2018).
ZIKV infection (2 papers, 2021 to 2025). "To identify possible functional alterations of microglia during ZIKV infection, we then conducted a detailed analysis of density, distribution, and morphology of Iba1+/TMEM119+ microglia in the st rad and st lac mol layers of the dorsal hippocampus CA1 using fluorescence microscopy." (PMID 34399779, 2021). "In addition to the lymphoid infiltrate, CD11b+TMEM119- macrophages also showed elevated CD38 levels, in line with their increased accumulation during ZIKV infection, suggesting functional activation and a potential role in NAD+ consumption." (PMID 41362627, 2025).
asthma (1 paper, 2021). "Third, asthma induction could increase peripheral macrophage infiltration; however, no change in Tmem119+ cell (microglia) content was observed following OVA or HDM treatment." (PMID 34880260, 2021).
brain inflammation (1 paper, 2021). "In contrast, myeloid cells recruited into the lesions in the course of brain inflammation in rodents and humans do not express TMEM119." (PMID 33482848, 2021).
brain injury (1 paper, 2018). Acute and chronic (see also brain INJURIES, CHRONIC) injuries to the brain, including the cerebral hemispheres, CEREBELLUM, and brain STEM. "Our results showed that Tmem119 expression significantly decreased on day 1 post-ICH, suggesting that it may participate in microglial function after acute brain injury." (PMID 30687011, 2018).
Cerebral ischemia (1 paper, 2024). Restriction of arterial blood supply to the brain associated with insufficient oxygenation to support the metabolic requirements of the tissue. "The current study demonstrated the activation of astrocytes and microglia 24 hours after cerebral ischemia and found that knocking out TMEM166 significantly inhibited the activation of TMEM119-positive microglia, but not GFAP-positive astrocytes." (PMID 37611898, 2024).
cholesteatoma (1 paper, 2023). A pathologic process characterized by the proliferation of keratinizing squamous epithelium resulting in the accumulation of keratin and cells in the middle ear and/or mastoid. "The expression of TMEM119 and PMEPA1 may reflect the characteristics of subcluster 8; these genes may promote the development and progression of bone destruction in cholesteatoma." (PMID 37537159, 2023).
cyst (1 paper, 2022). A sac-like closed membranous structure that may be empty or contain fluid or amorphous material. "Moreover, we found that cell type-specific TMEM119 staining also occurred at the 3D-cyst." (PMID 35789843, 2022).
experimental autoimmune encephalomyelitis (1 paper, 2023). An autoimmune demyelinating disease of the central nervous system that is produced experimentally in animals by the injection of homogenized brain or spinal cord in Freund's adjuvant. "Expression levels of TMEM119 are downregulated in experimental models of acute inflammation such as experimental autoimmune encephalomyelitis (EAE)." (PMID 36721258, 2023).
glaucoma (1 paper, 2024). Increased pressure in the eyeball due to obstruction of the outflow of aqueous humor. "In our previous study, where we implemented the new multifactorial glaucoma model, increased numbers of Iba1+ microglia/macrophages were noted in CTGF and CTGF+ONA retinae, while more Tmem119+ and Iba1+ microglia could be observed in CTGF+ONA mice." (PMID 38515755, 2024).
intracerebral hemorrhage (1 paper, 2021). A cerebrovascular disorder characterized by bleeding into one or both cerebral hemispheres including the basal ganglia and the cerebral cortex. "However, recent data may contradict the stability of TMEM119 in the context of injury by illustrating that Tmem119 transcripts are decreased post-injury in a model of intracerebral hemorrhage." (PMID 33618737, 2021).
knee osteoarthritis (1 paper, 2023). "Two high-confidence effector genes, WSCD2 and TMEM119, reside in the same genomic locus, which colocalizes for type 2 diabetes and knee osteoarthritis with a posterior probability of 99.9%." (PMID 37433298, 2023).
medulloblastoma (1 paper, 2022). A malignant, invasive embryonal neoplasm arising from the cerebellum. "To characterize and further delineate the location of resident microglia and infiltrating peripheral myeloid cells in the brain and within Myc/p53DD medulloblastomas, we performed IHC for two myeloid cell markers, Iba1 and Tmem119." (PMID 35309309, 2022). "Using IHC, we observed an abundance of Iba1+ cells throughout medulloblastomas and an absence of Tmem119+ cells, suggesting intratumoral Iba1+ cells were not microglia." (PMID 35309309, 2022).
myocardial infarction (1 paper, 2022). Gross necrosis of the myocardium, as a result of interruption of the blood supply to the area, as in coronary thrombosis. "Rapidly fatal myocardial infarctions were associated with absent or low density of TMEM119-positive profiles in cytospin preparations." (PMID 35821334, 2022).
Neurodegeneration (1 paper, 2021). Progressive loss of neural cells and tissue. "However, several studies revealed that in homeostatic conditions, microglia express high levels of TMEM119, while in neurodegeneration disorders microglial cells show a great reduction." (PMID 33482848, 2021).
osteoarthritis (1 paper, 2023). A noninflammatory degenerative joint disease occurring chiefly in older persons, characterized by degeneration of the articular cartilage, hypertrophy of bone at the margins and changes in the synovial membrane. "Knockout mice for TMEM119 show phenotypes related to both osteoarthritis and type 2 diabetes, such as decreased body weight, impaired osteoblast differentiation, and decreased compact bone thickness." (PMID 37433298, 2023). "The overexpression of TMEM119 in degraded cartilage from individuals with osteoarthritis supports the evidence of an increase in bone formation in later stages of the disease." (PMID 37433298, 2023).
pneumococcal infection (1 paper, 2022). Infections with bacteria of the species streptococcus pneumoniae. "Quantification analysis of the protein band intensities confirmed the significant increase of IFN-γ and the significant decrease of TMEM119 from 4 to up to 72 h of pneumococcal infection." (PMID 36036510, 2022). "In line with what was reported in the literature, we observed a consistent decrease of TMEM119 expression in brain homogenates from 4 to 72 h of pneumococcal infection." (PMID 36036510, 2022).
pneumococcal meningitis (1 paper, 2022). An acute purulent infection of the meninges and subarachnoid space caused by Streptococcus pneumoniae, most prevalent in children and adults over the age of 60. "Therefore, to assess a local neuroinflammatory response specific to microglia, we also measured by Western blotting the expression of the microglial-specific marker TMEM119 in the brain tissue of the rats at different time points of pneumococcal meningitis." (PMID 36036510, 2022).
retinal degeneration (1 paper, 2019). Degeneration of the retina. "In contrast, in RCS rats we saw Iba1-positive and TMEM119-positive cells, whose numbers varied during the course of retinal degeneration, over the first 90 post-natal days." (PMID 31402855, 2019).
tumor (51 papers, 2019 to 2026). "TMEM119 correlated with immune checkpoint genes, tumour mutational burden, and microsatellite instability." (PMID 40219804, 2025). "Regarding tumour mutational burden in STAD, TMEM119 expression was found to be significantly inversely associated with tumour mutational burden (r = –0.36, P < 0.0001), and the tumour mutational burden score was higher in the low TMEM119 expression group." (PMID 40219804, 2025). "Further survival analysis showed that patients with STAD with low tumour mutational burden and high TMEM119 expression had the worst prognosis." (PMID 40219804, 2025). "Several other groups have shown a reduction in Tmem119 gene expression in neurodegeneration and tumor-associated microglia." (PMID 38308250, 2024). "The level of TMEM119 protein expression was shown to be strongly associated with tumour size, clinical stage, distant metastases, and overall survival time." (PMID 38966281, 2024). "Next, we used the established microglia marker Transmembrane Protein 119 (TMEM119) to identify tumor-associated microglia in our mGBM models." (PMID 34298846, 2021). "Immunofluorescence (IF) staining for CD68 and TMEM119 on brain sections from an independent cohort confirmed that CD68+TMEM119- MDMs densely populated the tumor core, while CD68+TMEM119+ microglia were enriched at the tumor periphery." (PMID 41503214, 2026). "Immunohistochemistry staining showed a significant presence of CD68+ macrophages infiltrating the tumor core, while only a few TMEM119+ microglia were found." (PMID 39781357, 2025). "The present study explored the immune implication of TMEM119 in STAD, and revealed that elevated TMEM119 expression in STAD correlates with poor patient prognosis and is closely linked to the tumour microenvironment." (PMID 40219804, 2025). "For example, the immune role of TMEM119 in the tumour microenvironment of STAD was analysed and predicted mainly using bioinformatics methods, and was not validated." (PMID 40219804, 2025). "Tmem119+Arg1+ cells were rarely observed in the tumor core in either vehicle- or peptide-treated mice." (PMID 40281508, 2025). "Patients with high levels of TMEM119 expression were found to have higher ESTIMATEScore, ImmuneScore, and StromalScore in the tumour microenvironment." (PMID 40219804, 2025). "TMEM119, indicative of microglia, showed increased presence in the tumor microenvironment and adjacent brain tissue of saline‐treated mice, signifying heightened microglial activation." (PMID 40249282, 2025). "Consistent with the previous study, more TMEM119+ microglia cells were presented in tumor surrounding tissues." (PMID 39781357, 2025). "In tumor-bearing mice, microglia (Tmem119+) remained dominant, constituting ~ 65% of all myeloid cells, but were displaced from the tumor core by infiltrating MDMs (Gal-3+)." (PMID 40642066, 2025). "Tmem119+ cells (microglia) were consistently found at the invasive tumor edge and in the surrounding brain tissue, and displayed low or undetectable levels of Arg1." (PMID 40281508, 2025). "CD68+ infiltrating macrophages were predominantly recruited to the tumor core, whereas TMEM119+ resident macrophages (microglia) were mainly clustered in invasive islands." (PMID 39781357, 2025). "In the 3D model, M2-polarised macrophages (CD68 + CD163 + TMEM119 -) that had been validated by ICC were co-cultured with tumour cells." (PMID 40420192, 2025). "Overall, the present study substantially elucidates the role of TMEM119 in the tumour microenvironment in STAD, providing novel insights into its evaluation as a biological prognostic biomarker and immunotherapeutic target." (PMID 40219804, 2025). "CD68+ infiltrating macrophages were predominantly in the tumor core, and TMEM119+ resident macrophages (microglia) were clustered in invasive islands." (PMID 39781357, 2025). "To gain better information on their amount and organization within the whole tumor, we performed TMEM119 whole-mount immunofluorescences at D21 and D28." (PMID 39278921, 2024).